ZNF75A (zinc finger protein 75A)
Description:
May be involved in transcriptional regulation.
Synonyms: FLJ31529
Tractability: No criterion of Open Targets' tractability assessment is met for any kind of drug.
Gene: Protein-coding gene on chromosome 16 (3,305,406 to 3,318,852, forward strand). Ensembl gene ENSG00000162086.
Subcellular location: Nucleus
Subcellular location (Human Protein Atlas): Nucleoplasm; Nucleoli fibrillar center
Pathways (Reactome):
Gene expression (Transcription): Generic Transcription Pathway
Gene Ontology:
Molecular function: protein binding; sequence-specific double-stranded DNA binding; DNA-binding transcription factor activity, RNA polymerase II-specific; RNA polymerase II transcription regulatory region sequence-specific DNA binding
Biological process: regulation of transcription by RNA polymerase II; regulation of DNA-templated transcription
Cellular component: nucleus
Genetic constraint (gnomAD): Loss-of-function variants: 27 observed, 39.01 expected, observed/expected ratio (o/e) 0.69, 90% interval 0.51 to 0.95. The upper end of that interval is the gene's LOEUF score, 0.95, which puts it in group 4 of 6, group 1 being the genes least tolerant of losing a copy. Missense variants: 509 observed, 504.93 expected, observed/expected ratio (o/e) 1.01, 90% interval 0.94 to 1.09. Synonymous variants: 197 observed, 169.65 expected, observed/expected ratio (o/e) 1.16, 90% interval 1.03 to 1.31.
Homologues: Orthologues: macaque ZNF75A (97% identical), dog ZNF75A (80% identical), chimpanzee ZNF75A (55% identical). Paralogues in human: ZNF75D (64% identical), ZKSCAN1 (28% identical), ZNF263 (28% identical), ZNF394 (27% identical), ZKSCAN3 (27% identical), ZKSCAN4 (27% identical), ZNF213 (27% identical), ZNF397 (27% identical), ZSCAN12 (26% identical), ZSCAN25 (26% identical), ZNF449 (26% identical), ZSCAN22 (26% identical), and 18 more.
Diseases named in the same sentence as ZNF75A in open-access papers:
ZNF75A is named in the same sentence as 1 disease in open-access papers, as found by Europe PMC text mining. Sharing a sentence is not in itself a finding about the gene and the disease. The quoted sentences say what the papers report.
frontotemporal dementia (1 paper, 2021). Frontotemporal dementia (FTD) comprises a group of neurodegenerative disorders, characterized by progressive changes in behavior, executive dysfunction and language impairment, as a result of degeneration of the medial prefrontal and frontoinsular cortices. "The exceptions were FAM71B p.I318T, which was identified in a patient with frontotemporal dementia, and ZNF75A p.Q212E, which was identified in two of three members of another multi-incident family from the Queensland Parkinson’s Project, family #006." (PMID 33802862, 2021).